MBP (myelin basic protein)
Diseases named in the same sentence as MBP in open-access papers (continued):
Sharing a sentence is not in itself a finding about the gene and the disease.
Gliosis (3 papers, 2012 to 2023). Gliosis is the focal proliferation of glial cells in the central nervous system. "Indeed, it has been suggested that a proliferation of mixed-phenotype glial cells, which were found to be increased in the pathogenic white matter, contribute to this gliosis in MBP-/- mice." (PMID 24188129, 2013). "We first confirmed that cuprizone induced similar levels of demyelination and gliosis in the Myrf-Het;Nestin-tdT and the Myrf-cKO;Nestin-tdT mice based on MBP and Eriochrome Cyanine stainings, and on GFAP and Iba1 stainings." (PMID 36779010, 2023).
hepatitis B (3 papers, 2005 to 2024). "The MBP and MOG share homologies with the antigen of hepatitis B, HBsAg." (PMID 25405025, 2014).
Hypertension (3 papers, 2015 to 2022). The presence of chronic increased pressure in the systemic arterial system. "Corroboratively, hypertension also decreased density of myelin basic protein (MBP) immunoreactivity by 32 ± 10% in PFC (p = 0.008), but not in HIPP (p = 0.621)." (PMID 35812238, 2022).
intracerebral hemorrhage (3 papers, 2019 to 2025). A cerebrovascular disorder characterized by bleeding into one or both cerebral hemispheres including the basal ganglia and the cerebral cortex. "Intracerebral hemorrhage induced microglial activation and myelin basic protein (MBP) loss in WM." (PMID 31556245, 2019). "Research indicates that the apoptosis of oligodendrocytes following intracerebral hemorrhage (ICH) leads to the degradation of MBP and can trigger neuronal apoptosis." (PMID 40332557, 2025). "MBP levels on days 0–3 post-SAH were significantly higher among poor outcome patients (p < 0.001), non-survivors (p = 0.005), patients who underwent intracranial intervention (p < 0.001) and patients with intracerebral haemorrhage (ICH; p < 0.001)." (PMID 31915942, 2020).
neuroblastoma (3 papers, 2012 to 2020). Neuroblastoma (NB) is the most common solid, extracranial childhood tumor. "Using our SC-like cells conditioned medium collected on day 10 (because of the highest expression of SC makers, such as S100, GFAP, and MBP) successfully induced the neurite outgrowth in a neuroblastoma cell line, SH-SY5Y cells." (PMID 33322066, 2020). "Moreover, a recent study demonstrated that over-expression of HNRNPC2 in a human neuroblastoma cell line up-regulated the message level of MBP." (PMID 22737209, 2012).
Obesity (3 papers, 2020 to 2024). Accumulation of substantial excess body fat. "To further investigate the impact of HCHF and obesity on myelin, we measured the immunoreactivity of two myelin proteins, myelin-basic protein (MBP) and myelin proteolipid protein 1 (PLP1) in the striatum and the somatosensory cortex." (PMID 38538727, 2024). "However, no changes in MBP levels were found in brain sections of WD-fed C1qa KO compared with CD-fed WT and C1qa KO mice, indicating that deficiency of C1QA prevented the obesity-induced degradation of myelin." (PMID 32273396, 2020).
optic neuritis (3 papers, 2021 to 2025). Optic neuritis is inflammation of the optic nerve, the nerve that carries the visual signal from the eye to the brain.The conditionmay cause sudden, reduced vision in the affected eye(s). "ON demyelination and optic neuritis were obvious at 3 wpi, evidenced by significant loss of myelin basic protein (MBP) and infiltration of inflammatory T-cells and macrophage." (PMID 34707482, 2021). "MBP, essential for nerve myelination, was utilized to evaluate myelin status, while Brn3a, expressed in retinal ganglion cells (RGCs), was employed to assess neuronal survival in the context of optic neuritis." (PMID 40849530, 2025).
paraplegia (3 papers, 2005 to 2013). Complete paralysis of the lower half of the body including both legs, often caused by damage to the spinal cord. "Two of the patients showed an elevation of the cerebral spinal fluid (CSF) protein before development of paraplegia; one also showed a rise in myelin basic protein associated with his myelopathy." (PMID 18937872, 2008). "Increasing evidence has shown that total CSF protein, or more specifically, the myelin basic protein, may be elevated before development of paraplegia." (PMID 18937872, 2008). "Clinical signs of EAE were evident in MBP-treated Lewis female rats from the 8th day after first immunization inducing an acute monophasic disease progression resulting in paraplegia (clinical score of 4) or moribund state (clinical score of 5) on or around the 12th day." (PMID 15869713, 2005). "Treatment of SJL/J mice with SOCS1-KIR beginning 12 days post-immunization with myelin basic protein (MBP) resulted in minimal symptoms of EAE, while most control treated mice developed paraplegia." (PMID 24391643, 2013).
plexiform neurofibroma (3 papers, 2009 to 2021). An elongated and multinodular neurofibroma, formed when the tumor involves either multiple trunks of a plexus or multiple fascicles of a large nerve, such as the sciatic. "We found decreased gene expression on the SC differentiation/myelination markers (PMP22, MPZ, and MBP) in both mouse and human plexiform neurofibromas versus WT nerve controls." (PMID 31032403, 2019). "Plexiform schwannoma is distinguished from plexiform neurofibroma by the presence of vimentin and myelin basic protein in addition to being strongly positive for the S100 protein." (PMID 19568560, 2009).
primary progressive MS (3 papers, 2019 to 2025). "In a recent study, we showed that the prevalence of CD8+CD20+ T cells in CSF of patients with primary progressive MS was associated with the concentration of myelin-debris in the form of myelin basic protein (MBP) and development of new T2-weighted lesions." (PMID 40458400, 2025). "MBP-specific Th17 and Th1 cells are higher in both primary progressive MS (PPMS) and SPMS, suggesting therapeutic approaches restoring Teff:Treg balance may not only benefit RRMS, but also progressive MS." (PMID 33411696, 2021).
proteinopathy (3 papers, 2014 to 2024). "Deamidation of Gln residues favors the proteolysis of dysfunctional proteins via the ubiquitin proteasome system, but Gln deamidation of brain proteins including MBP is also strongly associated with proteinopathy which may resist the degradation of dMBP by the ubiquitin proteasome system." (PMID 26983404, 2016). "Previous studies have also identified that changes in the molecular composition of MBP influence white matter pathology in vascular dementia (VaD), and that excess DPMs promote proteinopathy and neurodegeneration in both AD and VaD." (PMID 26983404, 2016).
tauopathy (3 papers, 2020 to 2025). Neurodegenerative disorders involving deposition of abnormal tau protein isoforms (tau proteins) in neurons and glial cells in the brain. "Immunostaining confirmed a significant loss of OLIG2-positive cells and MBP-positive myelinated neurites in the hippocampus of tauopathy mice." (PMID 41331787, 2025). "Our results showed that SLIT2, a secreted signaling protein that acts extracellularly through ROBO receptors, is significantly increased in MBP-positive neurites in tauopathy brain." (PMID 41331787, 2025). "Co-immunostaining of SLIT2 and MBP revealed increased SLIT2 expression in neurites and its colocalization with MBP-positive axons in tauopathy mice, which was markedly attenuated by Dap12 deletion." (PMID 41331787, 2025). "Immunohistochemical analysis of myelin basic protein (MBP) in the stratum radiatum of CA1 showed that PS19-E4 mice had a significantly lower coverage area of MBP relative to PS19-E3 mice, indicating that APOE4 leads to hippocampal myelin deficits in the context of tauopathy." (PMID 37863057, 2023).
breast carcinoma (2 papers, 2021 to 2023). "Hirao-Suzuki and colleagues have also reported that repeated exposure to MBP, but not to BPA, aggressively stimulated abnormal proliferation in breast cancer cells through the activation of estrogen receptor β-dependent signaling." (PMID 33922211, 2021).
chorioamnionitis (2 papers, 2018 to 2024). A morphologic finding indicating inflammation of the fetal sac membranes. "In the changes we observed, in addition to disrupted neuronal maturation, we found that chorioamnionitis also accelerated pre-oligodendrocyte maturation into myelinating oligodendrocytes, evidenced by an increase in myelin-associated genes including MBP and MAG." (PMID 38200558, 2024). "In a pre-clinical chorioamnionitis model, we showed that short-term (2 days) intra-amniotic exposure to lipopolysaccharide (LPS) resulted in systemic inflammation, overt microgliosis, and changes in myelin basic protein (MBP) immunoreactivity (IR) in the fetal ovine brain." (PMID 29673373, 2018). "At the gene level, chorioamnionitis decreased the expression of PDGFC and PDGFRA and increased the expression of MBP, MAG, and MOG, consistent with our finding of decreased MBP at the protein level." (PMID 38200558, 2024).
cyst (2 papers, 2011 to 2020). A sac-like closed membranous structure that may be empty or contain fluid or amorphous material. "Within the cyst, the majority of β-TubIII positive fibers also expressed GAP-43, whereas some of them were associated with MBP, indicating that myelination occurred at 8 weeks post-treatment." (PMID 21611127, 2011).
fragile X syndrome (2 papers, 2018 to 2022). A genetic syndrome caused by mutations in the FMR1 gene which is responsible for the expression of the fragile X mental retardation 1 protein. "P7 mice modeling Fragile X Syndrome demonstrated a reduced volume of the cerebellum together with an 80% reduction of MBP expression." (PMID 35726031, 2022). "Particularly, in a mouse model of fragile X syndrome, the cerebellum displays a transient reduction in MBP and 2’,3’-cyclic nucleotide 3’-phosphodiesterase (CNP) expression as well as myelination at PD7, later showing complete recovery at PD15." (PMID 30687009, 2018).
geographic atrophy (2 papers, 2014 to 2019). "The 18q23 variant (rs1789110), which occurs near the myelin basic protein (MBP) gene, demonstrated suggestive evidence of association with geographic atrophy." (PMID 31367973, 2019).
GM2 gangliosidosis (2 papers, 2020 to 2022). A group of recessively inherited diseases characterized by the intralysosomal accumulation of G(M2) GANGLIOSIDE in the neuronal cells. "Gene expression profile studies showed that the myelin basic protein gene was significantly lower in the cerebral cortex of GM2 gangliosidosis (Tay–Sachs and Sandhoff) patients than healthy individuals." (PMID 36003081, 2022). "Gene expression profile studies in the cerebral cortex of normal and GM2 gangliosidosis (Tay-Sachs and Sandhoff) patients revealed that the myelin basic protein gene, expressed by oligodendrocytes, was also significantly depressed." (PMID 32951593, 2020).
hypothyroidism (2 papers, 2017 to 2018). Abnormally low levels of thyroid hormone. "In accordance with our hypothesis, transitory hypothyroidism during demyelination, followed by T3/T4 pulses to favor oligodendrocyte maturation, increased Myelin Basic Protein (MBP) and Myelin Oligodendrocyte (MOG), two markers of maturing oligodendrocytes, in the corpus callosum and septum." (PMID 28875931, 2017).
infarction (2 papers, 2020 to 2021). A localised pathological necrosis of tissue resulting from obstruction of the blood supply usually by a thrombus, an embolus, or vascular torsion. "Unfortunately, follow-up data regarding infarction on head CT is incomplete, but in eleven patients sampled for MBP on days 9–12 post-SAH where follow-up scans are available, none of the MBP negative patients developed DCI, but all MBP-positive patients had evidence of DCI." (PMID 31915942, 2020).
Infertility (2 papers, 2011 to 2015). "This is consistent with the previous study of adult men attending an infertility clinic but inconsistent with a smaller study of pregnant women (n = 76) in which statistically significant inverse relationships were reported between urinary MBP and serum levels of free and total T4." (PMID 21749963, 2011).
joint disease (2 papers, 2019 to 2021). "Changes in the methylation levels of genes associated with skin/joint disease (MBP, OSBPL5, SNORD115, and HCG26) and joint disease (IL22, ELF5, PPP2R2D, PTPRN2, and HCG26) were found." (PMID 33869291, 2021). "Biological inference prioritized notable DMRs associated with skin disease (SIGLEC14, JAM3, PCOLCE, RXRB), skin and/or joint disease (MBP, OSBPL5, SNORD115, HCG26), and joint disease (IL22, ELF5, PPP2R2D, PTPRN2, HCG26)." (PMID 30779748, 2019). "Although few DMRs exceeded a 10% change in methylation, it is noteworthy that many of those which did play roles in the pathogenesis of skin disease (SIGLEC14, JAM3, PCOLCE, RXRB, ELF5, IL22), joint disease (MBP, HCG26, IL22, PPP2R2D, PTPRN2) or are known to be imprinted (OSBPL5, SNORD115)." (PMID 30779748, 2019).
liver cancer (2 papers, 2021 to 2022). An epithelial or non-epithelial malignant neoplasm that arises from the liver. "MBP-11901 is suggested as a novel therapeutic agent for the treatment of advanced or unresectable liver cancer." (PMID 35454900, 2022). "We observed that MBP-11901 showed a similar level of anticancer effect in liver cancer cell lines as that shown by sorafenib." (PMID 35454900, 2022). "We further verified the effectiveness of MBP-11901 by constructing a mouse model in which Hep3B and Huh-7 were subcutaneously transplanted in addition to the human liver cancer cell line HepG2." (PMID 35454900, 2022). "To compare the effectiveness of MBP-11901 and sorafenib, a major component of the primary treatment regime of clinical liver cancer, we performed cell viability assays using various liver cancer cell lines (HepG2, Hep3B, Huh-7, and PLC/PRF.5) and a normal liver cell line, AML12." (PMID 35454900, 2022). "Here, we presented multi-RTKi MBP-11901, an innovative targeted anticancer agent for HCC, suggesting it as a new therapeutic strategy for the treatment of liver cancer." (PMID 35454900, 2022). "We found that eosinophils activated by IL33 secreted MBP, indicating that the combination of KRG and NK cells suppressed metastatic liver cancer cells." (PMID 35011007, 2021). "However, MBP and IFNγ expression showed no significance in OS of liver cancer patients (data not shown)." (PMID 35011007, 2021).
metabolic syndrome (2 papers, 2017 to 2024). A cluster of metabolic risk factors for CARDIOVASCULAR DISEASES and TYPE 2 DIABETES MELLITUS. "In MS patients with metabolic syndrome treated with metformin, MBP-reactive cells secreting IFNg and IL17 were reduced, while Tregs were increased in number and regulatory function." (PMID 39684351, 2024). "Although we did not observe significant changes on WM in VBM and in MBP expression on a histological level in our model, there are different theories linking the metabolic syndrome with white matter alterations." (PMID 27734300, 2017).
microcephaly (2 papers, 2014 to 2021). A congenital or acquired developmental disorder in which the circumference of the head is smaller than normal for the person's age and sex. "Moreover, our results are consistent with the fact that the depletion or low EDNRB expression leads to defective B cell differentiation or intrinsic lymphoid defects, similar to that MBP reduction causes neurodegenerative disorders like microcephaly." (PMID 33891593, 2021). "In current study, the upregulation of GHR suggests that the alteration of this gene by ZIKV may lead to neurological impairments causing reported diseases, which further indicate that MBP and GHR are directly involved in the brain development and microcephaly." (PMID 33891593, 2021).
mood disorder (2 papers, 2012 to 2022). A cognitive disorder a disturbance in which the person's mood is hypothesized to be the main underlying feature. "Further supporting our findings, myelin basic protein expression was reduced in the postmortem FPC of patients suffering from mood disorders, but not in those with SCH." (PMID 22438888, 2012).
myelitis (2 papers, 2022 to 2025). An inflammatory process affecting the spinal cord. "MBP was found to be higher in both MOGAD and AQP4-IgG NMOSD patients when compared to MS, although this association was not consistent with a previous study showing MBP correlation with EDSS and length of myelitis." (PMID 35401423, 2022). "Crucially, the absence of CSF pleocytosis, autoantibodies (AQP4/MOG/MBP), and demyelinating markers differentiated this case from myelitis, while DSA confirmed the vascular etiology." (PMID 41137336, 2025).
nasal polyp (2 papers, 2011 to 2025). "H&E staining showed a characteristic inflamed pattern with infiltration of leukocytes, predominately eosinophils, in the nasal polyp, confirmed by the presence of the eosinophil-specific marker MBP." (PMID 40051617, 2025). "Immunohistochemical staining of serial sections for FABP1, SMA, CD163, and MBP was performed on 4-μm sections of paraffinized nasal polyp samples." (PMID 21829647, 2011).
neuropathy (2 papers, 2023 to 2024). A disorder affecting the nervous system that manifests with pain, tingling, numbness, and/or muscle weakness. "Possible explanations for the presence of albumin-cytological dissociation include intrathecal production and release of proteins such as IgG or MBP or neuropathy-induced dysfunction of the blood-nerve barrier." (PMID 38915835, 2024). "We used myelin basic protein (MBP) to further investigate the ameliorative effect of HBOT on PAC-induced neuropathy." (PMID 36982452, 2023).
periventricular leukomalacia (2 papers, 2020 to 2022). Periventricular leukomalacia (PVL) is a brain injury disorder characterized by the death of the white matter of the brain due to softening of the brain tissue. "In previous reports, degradation of white matter and reduced positive staining regions for MBP were observed in brain sections of an LPS-induced rat model of periventricular leukomalacia (PVL)." (PMID 33339379, 2020).
relapsing (2 papers, 2014 to 2022). "Several earlier reports have demonstrated the prophylactic efficacy of anti-VLA-4 mAb or antagonist treatment in either PLP139-151-induced relapsing EAE in SJL mice or bovine MBP-induced chronic relapsing EAE in the SJL/J mice." (PMID 24896098, 2014).
schwannoma (2 papers, 2013 to 2023). A benign, usually encapsulated slow growing tumor composed of Schwann cells. "Another gene, Myef2, is a transcriptional repressor of the myelin basic protein gene, the expression of which is usually up-regulated in nerve sheath myxomas and schwannomas." (PMID 36669641, 2023). "The pathological diagnosis was Schwannoma and immunohistochemical testing showed Vimentin (+), S-100 (+), MBP (+), CD56 (+), GFAP (+), Ki-67 (+), Desmin (−), SMA (−), EMA (−), CD34 (positive in tumor vessels)." (PMID 23432938, 2013).
systemic sclerosis (2 papers, 2022 to 2024). A chronic disorder, possibly autoimmune, marked by excessive production of collagen which results in hardening and thickening of body tissues. "We have identified anti-MBP as a potential antibody associated with morphea due to its increased expression in morphea compared to healthy controls and systemic sclerosis patients." (PMID 35073943, 2022). "In systemic sclerosis (SSc), myelin basic protein (MBP) and myelin oligodendrocyte glycoprotein (MOG) can act as potential targets within the central nervous system (CNS)." (PMID 39734406, 2024). "Myelin basic protein autoantibodies were found in greater frequency in morphea (n = 50, 71.4%) compared to systemic sclerosis (n = 2, 6.7%) and healthy controls (n = 7, 20%)." (PMID 35073943, 2022). "The morphea cohort exhibited a significantly increased median net fluorescence intensity (NFI) for MBP of 133 compared to 15.5 in matched healthy controls (p < 0.01) and 45.5 in systemic sclerosis patients (p < 0.01)." (PMID 35073943, 2022). "Of all the morphea cases, 71.4% exhibited increased MBP autoantibodies compared to 20% of healthy controls and 6.7% of systemic sclerosis cases by NFI." (PMID 35073943, 2022).